OR2W1 (olfactory receptor family 2 subfamily W member 1)
Description:
Odorant receptor.
Synonyms: hs6M1-15
Tractability: Antibody: its Gene Ontology location is reachable by antibodies, with high confidence; UniProt places it where antibodies can reach, with medium confidence; UniProt predicts a signal peptide or a membrane-spanning region.
Gene: Protein-coding gene on chromosome 6 (29,044,213 to 29,045,175, reverse strand). Ensembl gene ENSG00000204704.
Subcellular location: Cell membrane
Pathways (Reactome):
Sensory Perception: Expression and translocation of olfactory receptors; Olfactory Signaling Pathway
Gene Ontology:
Molecular function: olfactory receptor activity; G protein-coupled receptor activity
Biological process: detection of chemical stimulus involved in sensory perception of smell; G protein-coupled receptor signaling pathway
Cellular component: plasma membrane; membrane
Genetic constraint (gnomAD): Loss-of-function variants: 0 observed, 0.35 expected, observed/expected ratio (o/e) 0, 90% interval 0 to 1.86. That is too few expected variants to judge how well the gene tolerates losing a copy. Missense variants: 366 observed, 403.33 expected, observed/expected ratio (o/e) 0.91, 90% interval 0.83 to 0.99. Synonymous variants: 133 observed, 145.87 expected, observed/expected ratio (o/e) 0.91, 90% interval 0.79 to 1.05.
Homologues: Orthologues: chimpanzee OR2W1 (98% identical), macaque OR2W1 (96% identical), mouse Or2w1 (85% identical), rat Or2w1 (84% identical), mouse Or2w1b (84% identical), dog OR2W1 (82% identical). Paralogues in human: OR2W3 (58% identical), OR2G3 (58% identical), OR2C3 (54% identical), OR2G2 (54% identical), OR2J3 (54% identical), OR2G6 (53% identical), OR2J1 (53% identical), OR2B6 (53% identical), OR2J2 (53% identical), OR2B3 (53% identical), OR2H1 (52% identical), OR2H2 (52% identical), and 80 more.
Diseases named in the same sentence as OR2W1 in open-access papers:
OR2W1 is named in the same sentence as 1 disease in open-access papers, as found by Europe PMC text mining. Sharing a sentence is not in itself a finding about the gene and the disease.
OR2W1 shares sentences with these, for which no sentence is quoted: Burkitt lymphoma (1 paper).